ALB (albumin)
Diseases named in the same sentence as ALB in open-access papers (continued):
Sharing a sentence is not in itself a finding about the gene and the disease.
tumor (continued). "Dp_ROI_Low, tumor size, serum albumin, platelet count, and lymphocyte count were independently related to high WHO/ISUP nuclear grade, and a nomogram was constructed for the multivariable logistic model." (PMID 39695867, 2024). "Because tumour cells predominantly internalise albumin as nutrition through a pathway mediated by the glycoprotein gp60 (albondin), albumin can activate the corresponding receptor in the tumour vasculature." (PMID 39456987, 2024). "The current research attempted to address the suitability of bioactive Sambucus nigra extract entrapped in albumin-decorated nanostructured lipid carriers (NLCs) as a promising “adjuvant” in improving tumour penetration for multiple antitumour therapy." (PMID 39456987, 2024). "The differences in serum albumin, maximum tumor diameter, and six-and-twelve scores in the validation group were statistically significant." (PMID 38344175, 2024). "In a univariate model of OS, sex (p = 0.045), age (p = 0.17), vascular invasion (p = 0.19), albumin (p = 0.14) and tumor stage (p = 0.11) were significantly prognostic, at a 0.2 significance level." (PMID 38201652, 2024). "Tumor cells require a significantly higher supply of energy and building blocks (serum albumin represents both) necessary for their maintenance and proliferation." (PMID 39138299, 2024). "The strong associations between Myo-ALBI grade 3 and various poor prognostic features (such as older age, higher BMI, elevated INR, lower albumin, higher bilirubin, and higher tumor burden) further validate this novel grading system." (PMID 39456597, 2024). "Phenolic compounds, which are widely found in natural plants, are the most studied and encapsulated natural active ingredients in the albumin NPs for oncological application owing to their anti-tumor, anti-inflammatory, and anti-microbial capabilities." (PMID 39070787, 2024). "Studies have shown that neutrophil–lymphocyte ratio (NLR), prognostic nutritional index (PNI), platelet-lymphocyte ratio (PLR), albumin (ALB) levels and systemic immunoinflammatory index (SII) are linked to survival rates among tumor patients." (PMID 38722378, 2024). "This analysis particularly focused on eGFR, Albumin, and Tumor Size, which emerged as the most influential factors." (PMID 38519947, 2024). "Then he received the fourth cycle of albumin-bound paclitaxel with cisplatin based on the tumor response and the guideline." (PMID 39777344, 2024). "Based on this curve, we predicted that the number of articles published each year will steadily increase, indicating a growing interest among researchers in albumin NPs as anti-tumor drug carriers." (PMID 39070787, 2024). "This study investigated hepatic functional reserve using a combination of clinical parameters simultaneously, including LSWV, DPV, ALT, AST, ALP, γ-GGT, ALB, PT, and tumor volume." (PMID 38549933, 2024). "Univariate analysis revealed that pre-treatment albumin and INR along with well-characterized risk factors, including tumor burden (Milan criteria, index lesion size, and BCLC staging), AFP levels, and response to LDT, were all associated with TTP." (PMID 38201639, 2024). "LNC1004 is a fibroblast activation protein (FAP)-targeting radiopharmaceutical, conjugated with the albumin binder Evans Blue, which has demonstrated enhanced tumor uptake and retention in previous preclinical and clinical studies." (PMID 38825657, 2024). "Addressing the blood-brain barrier's (BBB) limitations on therapeutic efficacy, albumin and lactoferrin were selected as targeting ligands to enhance the penetration of these inhibitors into the tumor microenvironment." (PMID 39479443, 2024).
tumor (continued). "The early administration of IMAs, when the disease burden is low, the tumor biology is less aggressive and the immunological status expressed by serum albumin is preserved, seem to improve clinical outcome." (PMID 38298193, 2024). "Doxorubicin was formulated with the hybridization of albumin and chitosan and an enhanced anti-tumor effect was observed in HepG2 hepatocellular carcinoma cell line." (PMID 39494247, 2024). "The CONUT score contains three modules: serum albumin concentration, lymphocyte count, and total cholesterol concentration, which reflect the nutritional status and the degree of tumor-derived chronic inflammation." (PMID 38337485, 2024). "ALP, AST, and ALT parameters were statistically significantly higher in tumor-bearing mice compared to control (healthy) mice of the same strain, sex, and age, whereas albumin was lower in the CCA model compared to the control." (PMID 39061229, 2024). "This approach facilitates the concurrent assessment of the albumin conjugate of legubicin and its unbound metabolites in plasma, tumor, and tissues." (PMID 38398527, 2024). "Another potential strategy involves the complexation of cyanine dyes with natural biopolymers such as serum albumin, enabling their accumulation in tumor tissues based on the size of the complex." (PMID 39138299, 2024). "The burst of the keyword “reactive oxygen species” indicates that these ROS-based anti-tumor therapies (such as chemodynamic, photodynamic, and sonodynamic therapies) are hot topics in the field of albumin NPs in oncology." (PMID 39070787, 2024). "Drug carriers constructed based on the albumin–SPARC interaction can reach the tumor tissue or cells more efficiently." (PMID 38323081, 2024). "We observe that linkingprodrug to serum albumin achieves several goals: (i) it extends thecirculation half-life and enables RABiT to accumulate at higher levelsand for a longer time period in tumor tissue." (PMID 39071065, 2024). "The strong affinity between SPARC and albumin contributed to the enhanced utilization of nab-paclitaxel by tumor cells, thereby potentially augmenting the therapeutic efficacy." (PMID 38914827, 2024). "An ROC analysis was calculated for descriptive purposes only, yielding an AUC of the FARI for the endpoint of complete tumor resection of 0.688 (0.605–0.771), as compared to 0.654 (0.568–0.740) for fibrinogen alone and 0.656 (0.570–0.742) for albumin alone." (PMID 39409916, 2024). "Consistently, double immunofluorescence staining indicated that Smad4 was highly expressed in albumin+ hepatocytes in mouse HCC tumor tissues." (PMID 39346534, 2024). "The SHAP value confirmed that preoperative eGFR, albumin level, and tumor size had a significant impact on the occurrence of CKD after surgery." (PMID 38519947, 2024). "From a pharmacokinetic perspective, besides its favorable molecular size, albumin presence enhances tumor drug penetration." (PMID 39544430, 2024). "The prognostic nutritional index (PNI) is computed using the formula: PNI = 10 * albumin value (g/dl) + 0.005 * total lymphocyte count in peripheral blood (per mm3).This index can reflect the prognosis of tumor patients." (PMID 38966640, 2024). "In contrast, the GNRI was significantly correlated with a lower BMI, lower SMI, lower albumin levels, higher CRP levels, a lower Child-Pugh Score A, more blood loss, longer postoperative hospitalization, and a larger tumor size." (PMID 38612974, 2024). "SPARC is a glycoprotein from the extracellular matrix that enhances the accumulation of albumin inside the tumour by providing mediated transport to the subendothelial space." (PMID 39456987, 2024). "Nab-paclitaxel, a 130 nano-meter albumin-bound paclitaxel complex, binds to specific receptors on the surface of tumor vascular endothelial cells, facilitating the uptake of paclitaxel into tumor cells via albumin-mediated endocytosis." (PMID 38745137, 2024).
tumor (continued). "The independent risk factors for early recurrence of HBV-related HCC patients were tumor diameter >5 cm, albumin level <35 g/L, and MVI." (PMID 39286273, 2024). "Inhaled paclitaxel-loaded bovine serum albumin microparticle dry powders demonstrated selective interaction with adenocarcinoma cells and significant tumor growth inhibition in a mouse model of lung cancer." (PMID 39204164, 2024). "In summary, our research aids a fresh inclusion in early malignancy detection by analyzing liver serum enzyme levels (ALP, ALT, albumin, and TP) and tumor metabolic parameters." (PMID 38957833, 2024). "Albumin <2.5 mg/dL, the presence of neoplasm, and the need for dialysis were identified as additional risk factors in the acute phase." (PMID 39403394, 2024). "Regarding the association between IL-6 and clinical features, interestingly, IL-6 levels were found to be higher in subjects with poorly differentiated histology, higher tumor burden, lower albumin levels, and liver metastasis." (PMID 38672257, 2024). "By utilizing the marker genes of HCC tumor cells, such as albumin (ALB) and aldolase 2 (ALDOB), we distinguished the malignancy clusters from immune cells and stromal cells." (PMID 39095854, 2024). "Serum albumin has been shown to modulate the tumor microenvironment by influencing oxidative stress and inflammatory responses." (PMID 39600700, 2024). "It is important to note there were significant disparities between the two cohorts in terms of tumor size, Child–Pugh class, Albumin–Bilirubin score, platelet count, and fibrosis stage." (PMID 38392039, 2024). "Most studies indicate that albumin is a key indication of the prognosis of tumor patients and that it is the primary reflection of the nutritional condition of tumor patients." (PMID 38384810, 2024). "Examination of tumor vessel perfusion by infusion of NIR fluorescent IR800-labeled albumin revealed a significant reduction of in vivo tumor blood perfusion on Days 4 and 5 following T cell transfer." (PMID 39629126, 2024). "When precursors enter the bloodstream, they quickly assemble into nanoparticles with serum albumin and self deliver to the tumor area." (PMID 39421608, 2024). "RPLS scores were higher in tumours with advanced stage and lymph node invasion (3/4 cohorts with data available) and positively correlated with serum albumin, CA19-9, CEA and GGT." (PMID 37758326, 2024). "Patients with MVI exhibited larger tumor size, a higher rate of tumor pseudocapsule, and higher levels of albumin, globulin, and the albumin/globulin ratio compared to patients without MVI." (PMID 39367397, 2024). "Raised serum CA19-9, bilirubin, CEA, neutrophil-to-lymphocyte ratio (NLR), platelet-to-lymphocyte ratio (PLR) and tumour MMP9, and low serum albumin were most associated with poorer survival; however, the cutoff values used widely varied." (PMID 38398089, 2024). "Based on this theory, we understand that the rigid chloro-cyclohexenyl ring on the heptamethine backbone that forms the covalent albumin adducts plays an important role in tumor preferential accumulation of Ph790H." (PMID 39766055, 2024). "Our analysis identified age, Child–Turcotte–Pugh class B, and the albumin–bilirubin (ALBI) grade as independent predictors of tumor recurrence." (PMID 39766066, 2024). "Results: at the time of tumor diagnosis, high inflammatory biomarkers (c-reactive protein (CRP), interleukin-6 (IL-6)) and albumin serum levels were associated with impaired OS in PDAC patients, but not in patients with oAC." (PMID 38539528, 2024). "Cationized albumin (pI > 8) accumulates in tumor cells via AMT and can be integrated with anti-glioma drugs into a nanodrug delivery system to induce tumor cell death and retard growth." (PMID 39409919, 2024). "Three sets of data for MVI, tumor diameter, and serum albumin level were obtained from these cases for external validation of the model." (PMID 39286273, 2024).
tumor (continued). "Low serum ALB level known as Hypoproteinemia also harms the sensitivity of anti-tumor treatments and leads to an imbalance in the tumor microenvironment." (PMID 38834790, 2024). "Our results indicated that preoperative eGFR was the most important variable, followed by albumin level, tumor size, and calcium level." (PMID 38519947, 2024). "The core idea of nab technology is to bind therapeutic agents to albumin nanoparticles (usually ∼100–150 nm in size) to improve the solubility, bioavailability, and tumor targeting of the drugs." (PMID 39434967, 2024). "Albumin, known for its selective accumulation in tumor tissue, serves as a significant source of energy and nutrition for the proliferation of tumors." (PMID 38041687, 2024). "ABDT4 binds tightly to human/murine serum albumin and the resultant prolonged in vivo circulation allows adequate binding to Trop2 on the surface of tumour cells." (PMID 38565806, 2024). "The increased lipophilicity upon the modification with an albumin binder has also been observed using other tumor targeting agents, which resulted in higher background activity." (PMID 38610940, 2024). "Albumin also has several traits that motivate its use as an endogenous carrier specifically for tumor applications." (PMID 38383524, 2024). "Based on this theory, the tumor-specific accumulation of IR-783 can be supported by the concept of structure-inherent tumor targeting owing to its weak binding affinity to serum albumin." (PMID 38791347, 2024). "Presentation of ALB expression levels revealed that in CRC patient tumor tissues from the TCGA database, the levels of ALB mRNA and protein were notably upregulated in comparison to those found in normal tissues." (PMID 39096436, 2024). "The surface-modified albumin NPs enter the blood circulation and the tumor cells by recognizing the highly expressed receptors on the membranes of tumor cells." (PMID 39070787, 2024). "The proteins protocadherin 17 (A0A8I3PDN1) and albumin (A0A8I3MY51) were the most abundant in both groups composed of animals with neoplasms (GI and GII)." (PMID 39057100, 2024). "Pre-albumin < 20 mg/L was the only indicator that correlated significantly with a more frequent tumor dissemination on all three levels (level 1, 2, and 3: p-values 0.001, 0.006, and 0.018, respectively)." (PMID 38339372, 2024). "Previous studies have shown that age, tumor differentiation, size, serum alkaline phosphatase, albumin, and CA19-9 are independent predictors of prognosis in PC." (PMID 37955009, 2023). "Tumor burden (mean total number of cells) for the entire spinal cord was significantly reduced in mice treated with PNA compared to albumin vehicle (P<0.05)." (PMID 37213306, 2023). "These patients had a larger tumor volume (p = 0.008), higher total bilirubin levels (p = 0.022), and lower albumin levels (p = 0.015), probably reflecting impaired liver reserves." (PMID 37510175, 2023). "Under stress conditions, as in tumor tissue, the cancer cell takes up albumin as a source of energy and amino acids to a greater extent than normal cells." (PMID 37514119, 2023). "Yet, histochemical analysis of metastatic tumor in spinal cord showed that the mean total number of cells in spinal cord was significantly reduced in mice treated with PNA compared to albumin vehicle (P<0.05)." (PMID 37213306, 2023). "With respect to iBL over 1500 mL, low albumin level <4 g/dL, high CRP ≥ 0.2 mg/dL, and large tumor size were independent associated parameters by the multivariate analysis." (PMID 36980626, 2023). "Circulating β2M is a potential biomarker that reflects theoxidative stress, or dialysate contamination, that involved in mucosal immunity,tumor monitoring, immunoglobulin and albumin homeostasis." (PMID 39077409, 2023). "FHAB binds to albumin in the serum, which can target FcRn and GP60 receptors that are often upregulated in tumor endothelium to transport albumin into the TME." (PMID 38250068, 2023).
tumor (continued). "The degree of tumor malignancy, positive Ki67 expression, and serum albumin levels are important factors for the recurrence of imaging tumors." (PMID 38188302, 2023). "One suggested tumour distribution mechanism is receptor-mediated endocytosis of albumin by glycoprotein receptor (GP60 receptor or albondin)." (PMID 37049985, 2023). "Intraoperative peri-tumoral injections of [99mTc]Tc-albumin nanocolloids were performed, followed by removing the tumour and locoregional lymph nodes." (PMID 37444438, 2023). "In the present study, AFP, tumor size and albumin were identified as independent prognostic factors, which was consistent with previous studies and indicated high heterogeneity in such patients." (PMID 37434986, 2023). "Age, naïve or recurrence, sum of the size of the largest tumor nodule, the number of nodules, total bilirubin, albumin, AFP and DCP were selected as independent predictors of survival." (PMID 38007597, 2023). "Albumin is a prognostic tumor marker that has been of great interest; its level is closely related to nutritional and inflammatory status." (PMID 37353748, 2023). "The efficacy of human serum albumin and its accumulation in the tumor by conjugation with albumin have been reported in previous studies." (PMID 36979069, 2023). "This parameter was compared with the tumor-to-normal (T/N) activity ratio predicted by technetium-99m macro-aggregated albumin (99mTc-MAA) single photon emission computed tomography (SPECT) and microsphere activity distribution by 90Y PET." (PMID 38169929, 2023). "The albumin nanodelivery system is characterized by extended circulation and tumor targeting, both of which significantly improve the therapeutic effects of the drug." (PMID 38009779, 2023). "One strategy is based on the introduction of the Evans Blue (EB), a dye molecule that can reversibly bind to circulating albumin and, thus, increase tumor accumulation of the radiotracer." (PMID 37835533, 2023). "In this cohort, patients with more advanced disease and higher tumor burden had poorer performance status and concomitantly lower levels of albumin and higher levels of CRP." (PMID 37176111, 2023). "Nab‐paclitaxel exploits endogenous albumin transmission pathway to enhance the transportation across the monolayer endothelial cells and increase the penetration of paclitaxel to tumor cells, when compared to the conventional paclitaxel." (PMID 37334881, 2023). "FAPI-113 shares the same characteristic because of binding to albumin or other plasma proteins, although it did have the lowest half maximal effective concentration and highest tumor accumulation." (PMID 36835275, 2023). "Third, it has been shown that albumin-based nanoparticles have an average size of 100–200 nm, which is appropriate for accumulation in tumor tissue via the EPR effect." (PMID 36985529, 2023). "In vivo SGB-complex binds with albumin and accumulated 10 times more in tumor than in normal organs." (PMID 37627119, 2023). "Due to the presence of large amounts of albumin at the tumor site and in inflamed tissues, the protein has been first conjugated with drugs and then administered to target the tumor or inflamed tissue." (PMID 37836018, 2023). "Because the rapid reproduction of tumor cells requires a large number of nutrients, albumin can provide amino acids and energy, so that albumin-binding receptor Gp60 exists on the surface of tumor cells." (PMID 37177365, 2023). "In the present study, significant relationships were detected between APEX1 genotypes and the levels of BPDE-albumin adduct and the tumor biomarkers." (PMID 36287252, 2023). "After hemodynamics stabilization with intravenous fluid/albumin administration and blood transfusion, image evaluation showed perihepatic presumed blood retention and an intrahepatic large tumor." (PMID 37663557, 2023).